TDRD5 (tudor domain containing 5)
Description:
Required during spermiogenesis to participate in the repression transposable elements and prevent their mobilization, which is essential for the germline integrity. Probably acts via the piRNA metabolic process, which mediates the repression of transposable elements during meiosis by forming complexes composed of piRNAs and Piwi proteins and govern the methylation and subsequent repression of transposons. Required for chromatoid body (CB) assembly (By similarity).
Synonyms: TUDOR3; FLJ34823
Tractability: PROTAC: its protein half-life has been measured.
Gene: Protein-coding gene on chromosome 1 (179,591,613 to 179,691,272, forward strand). Ensembl gene ENSG00000162782.
Subcellular location: Cytoplasm
Gene Ontology:
Biological process: P granule organization; spermatid development; transposable element silencing by piRNA-mediated DNA methylation; cell differentiation; germ cell development
Cellular component: chromatoid body; pi-body; cytoplasm; synapse
Genetic constraint (gnomAD): Loss-of-function variants: 38 observed, 120.47 expected, observed/expected ratio (o/e) 0.32, 90% interval 0.24 to 0.41. The upper end of that interval is the gene's LOEUF score, 0.41, which puts it in group 1 of 6, group 1 being the genes least tolerant of losing a copy. Missense variants: 987 observed, 1,258.5 expected, observed/expected ratio (o/e) 0.78, 90% interval 0.74 to 0.83. Synonymous variants: 423 observed, 448.27 expected, observed/expected ratio (o/e) 0.94, 90% interval 0.87 to 1.02.
Homologues: Orthologues: chimpanzee TDRD5 (99% identical), macaque TDRD5 (96% identical), dog TDRD5 (84% identical), pig TDRD5 (84% identical), rat Tdrd5 (79% identical), rabbit TDRD5 (79% identical), mouse Tdrd5 (78% identical), tropical clawed frog tdrd5 (34% identical), Drosophila melanogaster qin (18% identical). Paralogues in human: TDRD6 (14% identical), TDRD15 (13% identical), TDRD1 (12% identical), TDRD7 (11% identical), TDRKH (8% identical), TDRD10 (5% identical).
Diseases named in the same sentence as TDRD5 in open-access papers:
TDRD5 is named in the same sentence as 10 diseases in open-access papers, as found by Europe PMC text mining. Sharing a sentence is not in itself a finding about the gene and the disease. The quoted sentences say what the papers report.
hepatocellular carcinoma (4 papers, 2020 to 2023). A malignant tumor that arises from hepatocytes. "It was reported that hepatocellular carcinoma patients with high expression of TDRD5 suffered poor survival." (PMID 36895014, 2023). "The TDRD5 is involved in the DNA methylation and has prognostic value for patients with hepatocellular carcinoma." (PMID 35488327, 2022). "TDRD5 has significant prognostic value for hepatocellular carcinoma (HCC)." (PMID 32828126, 2020).
Azoospermia (3 papers, 2018 to 2023). Absence of any measurable level of sperm,whereby spermatozoa cannot be observed even after centrifugation of the semen pellet. "Previous studies found that TDRD5 was abnormally expressed in the testes of individuals with azoospermia." (PMID 36980830, 2023). "The aim of the present study was to investigate the role of HIWI2 rs508485 (T>C) and HIWI3 rs11703684 (C>T) polymorphisms and mutational analysis of TDRD5 gene in idiopathic non-obstructive azoospermia in a case-control study including 226 non-obstructive azoospermia patients and 200 fertile males." (PMID 29317647, 2018).
male infertility (2 papers, 2012 to 2023). The inability of the male to effect fertilization of an ovum after a specified period of unprotected intercourse. "A similar fragmentation of chromatoid bodies has been observed in other mouse mutants of RNA processing pathway proteins with male infertility phenotype, implying importance of their structural integrity (Miwi, Tdrd5, and Tdrd6)." (PMID 23166510, 2012). "TDRD5 protein is essential for pachytene piRNA biogenesis and may play an important role in male infertility." (PMID 36980830, 2023).
colon cancer (1 paper, 2020). "In our study, it was found that TDRD5, TDRD6 and TDRD7 are differentially expressed in CRC, and further studies on the role of these three genes in colon cancer are needed." (PMID 32828126, 2020).
tumor (2 papers, 2013 to 2023). "In our research, TDRD5 was remarkably upregulated in tumour samples and was identified as a prognostic factor for CRC patients (P < 0.001, HR = 1.431, CI:1.173–1.746))." (PMID 36895014, 2023).
TDRD5 also shares sentences with these, for which no sentence is quoted: Infertility (3 papers); breast carcinoma (2); Obesity (1); Sertoli Cell-Only Syndrome (1); sterility (1).